LYZ (lysozyme)
Diseases named in the same sentence as LYZ in open-access papers (continued):
Sharing a sentence is not in itself a finding about the gene and the disease.
viral infection (18 papers, 2016 to 2025). "The evidence that viral infection has an impact on the immunological profile of chicks and reports the downregulation of GM-CSF in chicks; may be the cause of the lower level of lysozyme concentration." (PMID 39316350, 2024). "Lysozyme secretion has been shown to be inhibited by influenza virus, which may predispose to a severe secondary bacterial infection following a viral infection." (PMID 34696391, 2021). "The direct antiviral activity is important as it complements the immunostimulatory properties of lysozyme, suggesting that this natural peptide may play pharmacological and therapeutic roles in various pathological conditions where viral infections are the main cause." (PMID 38338396, 2024). "An analysis of the literature shows that lysozyme can be used both as a disinfectant for raw and processed foods and as a drug to combat viral infections in animals and humans." (PMID 38338396, 2024). "Further evidence for the role of lysozyme content in reducing viral infections comes from a study on Bombyx morii, an insect in which viral infections are controlled by a significant increase in the overexpression of C-lysozyme." (PMID 38338396, 2024). "For example, the presence of components such as mucosal-specific IgA antibodies, lactoferrin, and lysozyme inhibit viral infection." (PMID 35224541, 2022). "We emphasized the prognostic and therapeutic application of lysozyme in cancer, hypertension, and viral diseases." (PMID 34925025, 2021). "Oral lysozyme administration is a new medical therapy to enhance the immunity of the organism and then fight against viral infection." (PMID 34925025, 2021). "In our study, lysozyme activity and antibacterial activity were tested after 48 h of virus infection, which was the early stage of virus infection." (PMID 33276568, 2020). "Expression of Defensin, Cecropin A1, Cecropin B, Andropin, Drosocin, Drosomycin, Metchnikowin, Lysozyme S, Attacin-B, Attacin-C, Diptericin A, and Lysozyme X was found to be induced after viral infection in cell lines or adult flies." (PMID 32983149, 2020). "The heat-denatured lysozyme has also been shown to counteract viral infections that cause foot-and-mouth disease (FMDV: Foot and Mouth Disease Virus), a highly contagious viral infection in domestic and wild animals with cloven hooves, including cattle, water buffalo, sheep, goats, and pigs." (PMID 38338396, 2024). "This review for the first time examines, from a pharmacological point of view, all the relevant studies on the antiviral properties of lysozyme, analyzing its possible mechanism of action and its ability to block viral infections and, in some cases, inhibit viral replication." (PMID 38338396, 2024). "Moreover, lysozyme is highly conserved in the animal kingdom and plays an important role in the protection of the host from potential bacterial and viral infection." (PMID 38138044, 2023). "As lysozyme is an important AMP, deleterious polymorphisms can affect the structure and hence the function of LYZ C resulting in decreased immunity against infections including viral diseases." (PMID 35776277, 2022). "And lysozyme (LZM) played a crucial role in anti-virus infections in fish." (PMID 35499101, 2022). "Similarly, the gene encoding lysozyme LYZ, which is reported to stimulate the cellular and humoral defense mechanisms of fish and to provide protection against viral diseases, was also upregulated in addition to phospholipase A2 gene (pla2s), which has been reported to block viral entry into cells." (PMID 37622112, 2023). "Together, the clinical investigation of lysozyme in the treatment of cancer, hypertension, viral diseases, and others may provide novel insights into alternative therapies and the prognostic potential to predict patient’s outcomes and cancer recurrence probability." (PMID 34925025, 2021).
viral infection (continued). "In addition to neutrophil cleavage of these substances post-viral infection, SARS-CoV-2 infection downregulated in airway epithelia a complex of antimicrobial peptides, including CCSP, lactoferrin, and lysozyme over the 3–14 dpi interval." (PMID 40791384, 2025). "Lysozyme plays an important role in the non-specific immune system; its antiviral function has been described in higher vertebrates, yet further studies are required to understand its role during viral infections in teleost fish." (PMID 33187217, 2020). "Human lysozyme is an important natural non-specific immune protein that is highly expressed in breast milk and participates in the immune response of infants against bacterial and viral infections." (PMID 26961596, 2016).
fungal infection (17 papers, 2015 to 2025). "Corresponding to these groups, the group with a higher proportion of soldiers had a significantly greater degree of upregulation of the immune effectors (lysozyme and termicin) of the workers after pathogenic fungal infection." (PMID 35733990, 2022). "The results obtained for the other three tested AMPs were less impressive, but still significant with lysozyme and cecropin encoding genes showing a four-fold upregulation after 24 h of C. glabrata infection, suggesting that these AMPs constitute a later response to fight the fungal infection." (PMID 33573089, 2021). "This is a significant variation given that lysozyme expression was a reliable indicator of fungal infection and immune response in adult mosquitoes, with significant induction starting at the early stages of infection and in multiple mosquito species." (PMID 40863559, 2025). "In some cases, lysozyme can effectively degrade fungal wall and reduce their population through cationic activity, therefore can protect the insect from fungal infections in the gut." (PMID 40608704, 2025). "Four different types of AMPs (apolipophorin III, defensin, lysozyme, and transferrin) were also up-regulated upon the fungal infection." (PMID 35450074, 2022). "The effect of fungal infection on lysozyme expression was highly significant but differed between mosquitoes and with fungal strain." (PMID 34843477, 2021). "While lysozyme is induced by fungal infection in similar patterns in both mosquitoes, our results indicate that infections by B. bassiana elicit stronger responses than B. brongniartii." (PMID 34843477, 2021). "We observed an increase in the expression of the gloverin and lysozyme genes in the midgut in response to fungal infection." (PMID 32927906, 2020). "A significant absolute neutrophilia with significant elevations of lysozyme activity were present in dolphins with PC, which suggest a systemic response to a bacterial or fungal infection." (PMID 31231361, 2019). "Similar to our results, the expression of antimicrobial peptides such as lysozyme was reduced in P. xylostella and L. migratoria following fungal infection." (PMID 30498450, 2018). "Unlike the F or B treatments, the F+I treatment, which resulted in lethal mycosis, upregulated several antimicrobial host genes, including lysozyme, PRPs, termicin, and transferrins." (PMID 25837376, 2015). "All four AMPs were inducible to the fungal infection, in which larvae up-regulated the AMP expressions earlier than adults except lysozyme." (PMID 35450074, 2022). "Another line of evidence for lower PO activity resides in the upregulation of lysozyme and REL2 expression post-fungal infection." (PMID 29684026, 2018). "In contrast to the infection-modulated expression observed in adult mosquitoes, fungal infections in mosquito larvae failed to induce the antimicrobial effector lysozyme." (PMID 40863559, 2025). "Our results indicate that fungal infection elicits the expression of cecropin, defensin, diptericin, holotricin, and lysozyme, but do not affect those of attacin or gambicin." (PMID 36687607, 2022). "Expression of lysozyme and PPO in the Glanville fritillary butterfly was not up-regulated 24 h after injection with M. luteus cells, whilst in the silkworm, up-regulation of lysozyme in response to fungal infection occurred in two peaks, from 9 to 18 h, and then between 30 and 48 h." (PMID 30954680, 2019).
Obesity (16 papers, 2017 to 2024). Accumulation of substantial excess body fat. "Our findings add a new dimension to this complexity, demonstrating that lysozyme deficiency can protect against diet-induced obesity by modulating bacterial composition." (PMID 38364095, 2024). "Substantial levels of lysozyme in adipose tissue in association to obesity have been recently demonstrated in mice and humans." (PMID 35784480, 2022). "The expression of inflammatory markers as CD68, IL-6, TNFα and lysozyme is increased during obesity and associated with insulin resistance." (PMID 36432612, 2022). "Moreover, LYZ levels in plasma were significantly increased in obesity in direct link with obesity-associated metabolic disturbances and inflammatory parameters." (PMID 38703299, 2024). "Or alternatively, that lysozyme, not unlike leptin, also enhances innate and adaptive immune responses, therefore lysozyme may also be implicated in the two-way relationship between the obesity and immune status." (PMID 34578947, 2021). "Increased plasma lysozyme levels and activity are found in obese subjects, the plasma lysozyme might be protective on the development of obesity-associated metabolic disturbances." (PMID 34925025, 2021). "In contrast, a recent proteomics approach in obesity included in systematic review showed an increased protein abundance of LYZ in VAT of subjects with obesity compared to VAT of normoweight patients." (PMID 38703299, 2024). "LYZ abundance was found decreased in circulating samples including platelets or plasma of patients with obesity compared to lean control." (PMID 38703299, 2024). "Lysozyme's co-localization in mouse intestine with LBP, an inflammatory marker found in obesity and other metabolic conditions, supports the potential role of lysozyme in inflammation." (PMID 28053879, 2017). "Decreased expression of LYZ was found in intestine of subjects with obesity." (PMID 38703299, 2024). "Subjects with obesity have lower AMPs including alpha-defensin as well as reduced lysozyme with signs of increased endoplasmic reticulum (ER) stress in paneth cells and an altered function, potentially contributing to the obesity-associated shift in microbiome or vice versa." (PMID 32295104, 2020). "Differential gene expression revealed that genes associated with innate immune responses (LYZ), antigen processing and presentation (HLA-DRB1, HLA-DRB5, IFI30), as well as cell signaling and migration (VIM, RGS1, NCF) were upregulated in the HBC subset with pregravid obesity." (PMID 39872537, 2024). "To investigate the contribution of myeloid cell-expressed ASK1 to the development of obesity and glucose intolerance, we generated myeloid cell-specific ASK1 knockout mice (ASK1flox/flox, Lysozyme-cre+/−; ASK1Δmye) using the Cre-lox system." (PMID 32242025, 2020). "Treatment with 1 mM DB for 30 minutes also reduced α-defensin 5 expression by 37% ± 9% (P < 0.05) and lysozyme by 32% ± 9% (P < 0.05) but not α-defensin 6 expression in primary crypts from patients with obesity." (PMID 34784295, 2022). "DB induces an acute release of α-defensin 5 and lysozyme in crypts of individuals with obesity but not in lean individuals." (PMID 34784295, 2022). "However, FASN and LYZ were common in both approaches, suggesting an important implication of both genes in AT metabolism in lean and post-RYGB compared to obesity." (PMID 36432612, 2022).
breast carcinoma (15 papers, 1976 to 2025). "The high levels of both P and LYZ in MDA-MB 231 breast cancer cells can reasonably provide a causative explanation of RPL treatment effects on these cells." (PMID 40046560, 2025). "Our results reveal new properties of phosphocholine and LYZ with potential translational implications linked to the study of the transdifferentiation process of breast cancer cells and to therapeutical applications." (PMID 40046560, 2025). "In a study involving 177 breast cancer tissue sections, it was found that 126 of these sections exhibited positive LYZ staining in tumor cells as detected by immunohistochemistry." (PMID 40046560, 2025). "The presence of both phosphocholine and high levels of LYZ expression at the breast cancer cell–cell interface seems to create a vulnerability for this new photodynamic system under visible light exposure." (PMID 40046560, 2025). "Other altered genes in these patients are FRS2, LYZ, and CPSF6, all associated to breast cancer pathogenesis." (PMID 36860495, 2022). "Biologically active peptides from OVT and lysozyme can be employed in cancer treatments, including for colon and breast cancer, since they have reduced cytotoxicity against normal cells as well as interfere with cancer cell progression." (PMID 34976961, 2021). "Nanoassembly (NA) based on a D-α-tocopherol succinate (αTS) conjugated lysozyme (Lys) (Lys-αTS) was fabricated for tumor-selective delivery of curcumin (CUR) for breast cancer therapy." (PMID 29516756, 2018). "Serum lysozyme activity was measured in groups of untreated patients with malignant melanoma, hyperneophroma and breast carcinoma." (PMID 938609, 1976). "Treatment with a preparation containing self-assembled nanostructured lysozyme particles showed a tumor inhibition rate of 31.53 and a survival extension of 4–5 days in different murine tumor models, as well as an inhibition of breast cancer cell migration." (PMID 34976961, 2021). "Notably, a high LYZ staining score correlated with improved overall survival and relapse-free survival was observed, indicating that LYZ is a favorable prognostic factor in breast cancer patients." (PMID 40046560, 2025). "The detection of native lysozyme is important on its own right, for example, real-time monitoring of lysozyme concentration in biological fluids would act as an early warning for many diseases including bacterial infections, rheumatoid arthritis, breast cancer leukemia, and kidney disorders." (PMID 35214929, 2022). "Our results show significantly higher levels of P in MDA-MB 231 compared to nontumoral MCF-10A cells and high levels of LYZ expression with the presence of high-molecular-weight forms of LYZ in breast cancer cells, not detected in stem cells." (PMID 40046560, 2025). "Lysozyme, the next ranked hub-bottleneck of the GBC network, has been reported with high expression in the sera of patients with malignancies including cancers of lung, melanoma, and breast carcinomas." (PMID 32099604, 2019).
Alzheimer disease (14 papers, 2008 to 2025). A progressive, neurodegenerative disease characterized by loss of function and death of nerve cells in several areas of the brain leading to loss of cognitive function such as memory and language. "Alzheimer’s disease patients were reported to exhibit increased lysozyme levels in the cerebrospinal fluid." (PMID 38324617, 2024). "KWMTBOMO07068 is predicted to be a lysozyme capable of counteracting the formation of toxic amyloid-β species for Alzheimer disease." (PMID 34564249, 2021). "In a fly model of Alzheimer's disease for example, neuronal co-expression of lysozyme and amyloid-β1–42 diminished soluble and insoluble amyloid species, and prolonged survival of Aβ-expressing flies." (PMID 27525822, 2016). "Knowledge of the detailed mechanism by which proteins such as human αB- crystallin and human lysozyme inhibit amyloid beta (Aβ) peptide aggregation is crucial for designing treatment for Alzheimer's disease." (PMID 25422897, 2014). "Furthermore, the tear fluid of Alzheimer’s disease patients included considerably lower amounts of lysozyme, lipocalin 1, and lacritin, as well as higher levels of dermcidin." (PMID 36983883, 2023). "Thus in present study, two anti-tuberculosis drugs, i.e., pyrazinamide (PYZ) and D-cycloserine (DCS), also known for treatment for Alzheimer’s dementia, were checked for the anti-aggregation and anti-amyloidogenic ability on Aβ-42 peptide and hen egg white lysozyme." (PMID 26312749, 2015).
inflammatory bowel disease (14 papers, 2014 to 2025). A spectrum of small and large bowel inflammatory diseases of unknown etiology. "Hereditary amyloidosis associated with the p.Trp82Arg lysozyme variant in this new family is predominantly associated with mild upper gastrointestinal tract involvement and in some cases with inflammatory bowel disease." (PMID 25217048, 2014). "In fact LRRK2, a major susceptibility gene for inflammatory bowel disease (IBD), was found to recruit Rab2 to ISGs for the selective sorting of lysozyme during SG maturation in Paneth cells." (PMID 27751232, 2016). "Excessive release of LYZ can also lead to degradation of healthy tissues, such as intestinal epithelial barrier damage in inflammatory bowel disease." (PMID 41384115, 2025). "Elevated lysozyme production is found in various inflammatory conditions while patients with genetic risks for inflammatory bowel diseases demonstrate abnormal lysozyme expression, granule packaging, and secretion in Paneth cells." (PMID 38823640, 2024). "The supplementation of the exogenous hen egg white lysozyme has a significant anti-inflammatory effect in the treatment of inflammatory bowel disease." (PMID 34943746, 2021). "Elevated fecal lysozyme has been reported in patients with inflammatory bowel diseases (IBD)." (PMID 38823640, 2024). "Other potential markers of intestinal inflammation including antitrypsin, eosinophilic protein X, TNFα, or lysozyme have been suggested for diagnosing inflammatory bowel disease, which may be expanded to test for STH attributable intestinal morbidity." (PMID 33554091, 2021). "Loss of HPS1 impairs lysozyme secretion and alters the composition of intestinal microbiota, which may explain the susceptibility of HPS-associated inflammatory bowel disease." (PMID 33224134, 2020). "The lysozyme of the microbial source was also proposed for suppressing the growth and/or intestinal colonization of bacterial pathogens in the gastrointestinal tract, and in the treatment of irritable bowel syndrome or inflammatory bowel disease (Crohn’s disease and ulcerative colitis)." (PMID 34943746, 2021). "The aptasensor was designed to detect lysozyme, which is used as a biomarker for Inflammatory Bowel Disease (IBD), where lysozyme levels are up-regulated." (PMID 32354207, 2020).